CAMTA1 (calmodulin binding transcription activator 1)
Diseases named in the same sentence as CAMTA1 in open-access papers (continued):
Sharing a sentence is not in itself a finding about the gene and the disease.
colorectal cancer (1 paper, 2022). A primary or metastatic malignant neoplasm that affects the colon or rectum. "By contrast, Nfatc4 knockdown reversed the resistance of colorectal cancer cells to oxaliplatin caused by Camta1 knockdown." (PMID 35332122, 2022). "In addition, we show that protein phosphatase 3 catalytic subunit alpha (PPP3CA) is essential for the expression and phosphorylation of NFATc4 caused by Camta1 knockdown, as well as the proliferation, invasion, and chemoresistance of colorectal cancer cells." (PMID 35332122, 2022). "Here, we investigate the role of CAMTA1 in colorectal cancer by manipulating its expression through overexpression and knockdown and examining how these changes affect the resistance of colorectal cancer cells to oxaliplatin." (PMID 35332122, 2022). "Immunohistochemical staining and western blotting analyses of normal and colorectal cancer tissues showed a significantly low expression of Camta1 expression in colorectal cancer tissues, when compared to adjacent normal tissues." (PMID 35332122, 2022). "To investigate the levels of CAMTA1 and NFATc4, we performed qPCR, western blotting, and immunohistochemical staining experiments using normal and colorectal cancer tissues collected from patients during surgery." (PMID 35332122, 2022). "The mRNA level of NFATc4is negatively correlated with the mRNA level of CAMTA1 in colorectal cancer tissue." (PMID 35332122, 2022). "In order to further clarify the mechanism of action of CAMTA1/NFATc4 in oxaliplatin resistance in colorectal cancer, we analyzed the interaction between PPP3CA, CAMTA1, and NFATc4." (PMID 35332122, 2022). "Calmodulin-binding transcription activator 1 (CAMTA1) is involved in tumor growth and development, but its mechanisms of action in the development of colorectal cancer and chemoresistance are poorly understood." (PMID 35332122, 2022). "To understand these in vitro findings in an in vivo context, as well as to confirm the role of CAMTA1 in colorectal cancer growth and oxaliplatin resistance, we established a xenograft mouse model." (PMID 35332122, 2022). "Lastly, we use a xenograft mouse model to verify the role of CAMTA1 in oxaliplatin resistance in colorectal cancer and show agreement between in vitro and in vivo findings." (PMID 35332122, 2022). "In order to clarify the role of NFATc4 in the oxaliplatin resistance of colorectal cancer regulated by CAMTA1, we conducted clone formation experiments and apoptosis detection respectively." (PMID 35332122, 2022). "Taken collectively, these findings indicate that CAMTA1 can inhibit tumor growth and development, and that CAMTA1 is involved in the resistance of colorectal cancer to oxaliplatin." (PMID 35332122, 2022). "We performed western blotting and immunofluorescent staining experiments using CAMTA1-overexpressed and CAMTA1-silenced colorectal cancer cells." (PMID 35332122, 2022). "Thereafter, the effects of CAMTA1 overexpression and knockdown on the resistance of colorectal cancer cells to oxaliplatin, a common chemotherapeutic drug, were examined." (PMID 35332122, 2022). "Immunohistochemistry staining scores revealed a lower percentage of CAMTA1 immuno-positive cells in colorectal cancer tissues, when compared to that in normal tissues but a higher percentage of Ki-67, a cell proliferation marker, immuno-positive cells." (PMID 35332122, 2022). "We also confirmed such observations in NFATc4 knockdown cells, indicating that the negative regulation of NFATc4 by CAMTA1 is related to oxaliplatin resistance in colorectal cancer." (PMID 35332122, 2022). "We demonstrate that CAMTA1 expression in colorectal cancer tissues is significantly lower than that in normal colorectal tissues from humans." (PMID 35332122, 2022). "Taken collectively, these results indicate that CAMTA1 can inhibit colorectal cancer cell proliferation, invasion, and migration, which is consistent with its function as a tumor suppressor." (PMID 35332122, 2022).
colorectal cancer (continued). "To further confirm CAMTA1’s role in colorectal cancer, we established xenograft models and silenced CAMTA1." (PMID 35332122, 2022). "In conclusion, the negative regulation of NFATc4 by CAMTA1 is involved in the oxaliplatin resistance of colorectal cancer." (PMID 35332122, 2022). "Here, we found that CAMTA1 mRNA and protein levels in colorectal cancer tissues from different patients were significantly lower than those in paired adjacent normal tissues." (PMID 35332122, 2022). "To understand the role of CAMTA1 in colorectal cancer, we conducted CAMTA1 overexpression and knockdown experiments and examined the effects of these manipulations on cell migration and invasion in vitro." (PMID 35332122, 2022). "Subsequently, we examined the effects of Camta1 overexpression and knockdown on the resistance of colorectal cancer cells to oxaliplatin, a common chemotherapeutic drug." (PMID 35332122, 2022). "In order to further explore the mechanism of CAMTA1 regulating oxaliplatin resistance in colorectal cancer, we predicted the downstream target genes of CAMTA1 and analyzed the expression of NFATc4." (PMID 35332122, 2022). "To verify the role of CAMTA1 in oxaliplatin resistance in colorectal cancer, we established a xenograft mouse model and show agreement between in vitro and in vivo results." (PMID 35332122, 2022). "Here, we report the function of CAMTA1 in colorectal cancer." (PMID 35332122, 2022). "In colorectal cancer cells, CAMTA1 negatively regulates the expression of NFATc4." (PMID 35332122, 2022). "Compared with the control, the highest percentage of CAMTA1 immuno-positive cells was found in colorectal cancer tissues from mice treated with oxaliplatin, whereas the lowest percentage was found in colorectal cancer tissues in which Camta1 expression was silenced." (PMID 35332122, 2022). "To understand the role of CAMTA1 in colorectal cancer, we conducted CAMTA1 overexpression and knockdown experiments and examined the effects of these manipulations on cell migration and invasion using representative colorectal cancer cell lines." (PMID 35332122, 2022). "To understand the role of NFATc4, a transcription factor, in colorectal cancer, as well as to determine whether its expression could be affected by the manipulation of CAMTA1 expression, we used CAMTA1-overexpressed and CAMTA1-silenced colorectal cancer cells." (PMID 35332122, 2022). "We hypothesize that CAMTA1 knockdown can promote oxaliplatin resistance, thereby facilitating colorectal cancer growth." (PMID 35332122, 2022). "Furthermore, Camta1 knockdown upregulated nuclear factor of activated T cells, cytoplasmic 4 (Nfatc4) mRNA, and protein levels in colorectal cancer cells and downregulated the phosphorylated NFATc4 level." (PMID 35332122, 2022). "By contrast, compared with the control, the highest percentage of NFATc4 immuno-positive cells was found in colorectal cancer tissues from mice in which Camta1 expression was silenced, whereas the lowest percentage was found in colorectal cancer tissues from mice treated with oxaliplatin." (PMID 35332122, 2022). "In in vitro experiments, we show that the sensitivity of CAMTA1-overexpressed colorectal cancer cells to oxaliplatin was increased, whereas that of CAMTA1-silenced cells to oxaliplatin was decreased, indicating that CAMTA1 promotes the death of colorectal cancer cells exposed to this drug." (PMID 35332122, 2022). "To determine whether CAMTA1 overexpression or knockdown could affect the survival of oxaliplatin-treated colorectal cancer cells, we assessed the cell viability, apoptosis, colony formation, and performed western blotting experiments in which the levels of apoptosis-related proteins were measured." (PMID 35332122, 2022).
colorectal cancer (continued). "Taken collectively, these findings indicate that CAMTA1 overexpression can render colorectal cancer cells more sensitive to oxaliplatin, and thus, this approach may hold clinical promise in the future, although prolonged gene overexpression in rapidly growing tumors is presently a challenge." (PMID 35332122, 2022). "Previously, studies have reported that CAMTA1, a transcription factor, plays a key role in a variety of cancers, although its mechanism of action in colorectal cancer is not known." (PMID 35332122, 2022). "In qPCR experiments, we found that CAMTA1 was expressed by SW620, SW480, and HCT116 cells at comparable levels, and SW480 and SW620 cell lines were selected for further studies as representative colorectal cancer cells." (PMID 35332122, 2022). "Interestingly, NFATC4 knockdown can reverse the chemoresistance of CAMTA1-silenced colorectal cancer cells to oxaliplatin, and this cellular event is partly mediated by an interacting protein, PPP3CA, which together with CAMTA1, competitively binds to NFATc4." (PMID 35332122, 2022). "The levels of CAMTA1 mRNA were significantly lower in colorectal cancer tissues than that in paired adjacent normal tissues, whereas the NFATC4 mRNA level was significantly higher in colorectal cancer tissues." (PMID 35332122, 2022). "To determine whether CAMTA1, NFATc4, and PPP3CA interact in colorectal cancer cells, we performed qPCR, western blotting, and co-immunoprecipitation experiments." (PMID 35332122, 2022).
depression (1 paper, 2022). "Studies have found that CAMTA1 plays a role in memory production and recall, dysfunction of which is implicated in disorders such as down syndrome, schizophrenia, and depression." (PMID 36180424, 2022).
developmental and epileptic encephalopathy (1 paper, 2024). An epilepsy associated with developmental impairment that may be due to either the underlying etiology or the superimposed epileptic activity, or both. "Within the cohort of patients experiencing developmental and epileptic encephalopathy (DEE), WES has revealed genetic variants in novel genes (FGF12, GABBR1, GABBR2, ITPA, KAT6A, PTPN23, RHOBTB2, SATB2) and candidate epilepsy-associated genes (CAMTA1, FAT3, GABRA6, HUWE1, PTCHD1)." (PMID 39523358, 2024).
diabetes (1 paper, 2018). "The CAMTA1 gene product has been demonstrated to play an integral role in the regulation of microRNA profiles (i.e., miR-212/miR-132) and beta cell function, with the differential expression of transcript levels implicated in the pathogenesis of diabetes." (PMID 30524468, 2018).
hepatic (1 paper, 2025). "While the prognosis difference between the TFE3-subtype and CAMTA1-subtype hepatic EHE still needs to be further explored in a larger study cohort." (PMID 40040722, 2025).
Hyperglycemia (1 paper, 2021). An increased concentration of glucose in the blood. "Obesity, clinically evident as hyperglycemia or high blood glucose is known to increase the expression of miR-212-3p, possibly via calmodulin binding transcription activators CAMTA1 and 2 and its target genes, collectively increasing insulin secretion from beta cells in the pancreatic islets." (PMID 34827683, 2021).
ischemia (1 paper, 2024). A hypoperfusion of the BLOOD through an organ or tissue caused by a PATHOLOGIC CONSTRICTION or obstruction of its BLOOD VESSELS, or an absence of BLOOD CIRCULATION. "Validated targets of miR-129-5p are CAMTA1 (calmodulin-binding transcription factor), indicating a role of calcium under this condition, SOX4 (regulation of Wnt pathway), GALNT1 (modifying glycan structures), EIF2C3 and HMGB1, which has been shown to protect against ischemia/reperfusion injury." (PMID 39201485, 2024).
myoclonic dystonia (1 paper, 2022). "A myoclonic dystonia-predominant phenotype was also described which result from a novel CAMTA1 sequence variant." (PMID 36614124, 2022).
Neurodevelopmental delay (1 paper, 2022). "Several of the associated genes, including MAD1L1, CAMTA1, and ALDH1A2 have been implicated in neurodevelopmental delay, suggesting that differential DNAm may partly explain the biological mechanisms underlying the relationship between PTE and PAE and child neurodevelopment." (PMID 36180424, 2022).
Parkinson disease (1 paper, 2019). A progressive degenerative disorder of the central nervous system characterized by loss of dopamine producing neurons in the substantia nigra and the presence of Lewy bodies in the substantia nigra and locus coeruleus. "Moreover, both CAMTA1 and DENND4A were independently found to be ‘Master Regulators’ (MRs) of neurodegenerative disease transcriptional programs in an in vivo Parkinson’s disease model and a cultured motor neuron-based ALS model." (PMID 30357366, 2019).
pulmonary arterial hypertension (1 paper, 2021). Pulmonary arterial hypertension (PAH) is a group of diseases characterized by mean pulmonary artery pressure >20 mmHg and elevated pulmonary arterial resistance leading to right heart failure. "CAMTA1 was a regulator of nuclear factor of activated T cells signaling, which was linked to pulmonary arterial hypertension." (PMID 34809630, 2021).
Stroke (1 paper, 2022). Sudden impairment of blood flow to a part of the brain due to occlusion or rupture of an artery to the brain. "To investigate the CAMTA1 function implicated in stroke, we did knockout CAMTA1 gene in HEK 293T and SH-SY5Y cell lines by Crisper/Cas9." (PMID 36159397, 2022). "CAMTA1 also plays an essential role in cell cycle regulation in strokes." (PMID 36159397, 2022). "To understand the CAMTA1 function in stroke, we generated CAMTA1 knockout in SH-SY5Y cells." (PMID 36159397, 2022). "Our research focused on studying the function of CAMTA1 in strokes." (PMID 36159397, 2022). "Therefore, we suppose that CAMTA1 could regulate cyclin D1, and through this intermediate CAMTA1 could play a role in stroke." (PMID 36159397, 2022). "However, the involvement of CAMTA1 in stroke has not been reported." (PMID 36159397, 2022).
type 2 diabetes (1 paper, 2022). "In addition, Camta1 has been proved to regulate miR-132 to modulate insulin production and secretion in the pathology of the type 2 diabetes rat model." (PMID 35800215, 2022).
tumor (47 papers, 2010 to 2025). "The CAMTA1 gene encodes a transcription factor that has been implicated as a candidate tumor suppressor in neural cancers." (PMID 29996478, 2018). "For example, the fusion of the TAZ gene with the gene that encodes CAMTA1 transcription factor is responsible for the majority of cases documenting a rare tumor known as Epithelioid Hemangio-Endothelioma (EHE) that primarily affects soft tissues, including lung." (PMID 34845189, 2021). "EHEs have been characterized by tumor-specific WW domain-containing transcription regulator 1(WWTR1)-calmodulin-binding transcription activator 1 (CAMTA1) translocations, and recently, a novel Yes-associated protein 1 (YAP1)-transcription factor E3 (TFE3) gene fusion was identified in EHEs." (PMID 26840265, 2016). "Histologically, EHE is a malignant tumor composed of vascular endothelial cells accompanied by a distinctive myxoid-hyaline transformation of the mesenchyme with WWTR1::CAMTA1 and YAP1::TFE3 fusion genes." (PMID 39917171, 2025). "Another CAMTA1 rearranged case (case 7) had higher atypia and the tumor exhibited infiltrative growth into liver parenchyma." (PMID 40040722, 2025). "In our study, 2 of the 3 cases exhibited classic histology of CAMTA1-subtype, showing nests of epithelioid tumor cells with small, oval nuclei and intracytoplasmic vacuoles." (PMID 40040722, 2025). "The YAP1::TFE3 fusion was identified in one case (#130), and this tumour demonstrated unique morphology compared to tumours harbouring the more common WWTR1::CAMTA1 fusion." (PMID 37686662, 2023). "Compared with the control (i.e., siNC), tumor volume was increased in mice in which Camta1 expression was silenced." (PMID 35332122, 2022). "Their analysis of different candidate 1p36 tumor suppressor genes, such as Arid1a, Chd5, Camta1, and Kif1b, identified Arid1a as the gene with strongest correlation between expression levels and time to tumor onset." (PMID 34885007, 2021). "Paradoxically, in different contexts CAMTA1 is a candidate tumor suppressor in neuroblastoma and glioma." (PMID 29996478, 2018). "CHD5 is located at 1p36, together with other tumor suppressors including p73, CAMTA1, miR-34a, KIF1β, and CASZ1." (PMID 26943038, 2016). "lncCAMTA1 resides on chromosome 1 and orients in antisense direction with respect to calmodulin binding transcription activator 1 (CAMTA1), a critical tumor suppressor in many cancers." (PMID 27669232, 2016). "CAMTA1 has been reported as a tumor suppressor, which inhibits proliferation and activates differentiation programs in many cancer cells and cancer stem cells." (PMID 27669232, 2016). "The miR-9 target calmodulin-binding transcription activator 1 (CAMTA1) functions as a tumor suppressor." (PMID 26064134, 2015). "Among the MNA tumors (n=10), five tumor suppressor genes (among other genes) were underexpressed within the distal 1p: CAMTA1, KIF1B, PRDM2, FABP3, and CDKN2C; whereas MYCNOS and MYCN were the two top differentially upregulated genes on 2p." (PMID 23656755, 2013). "CAMTA1, a putative tumor suppressor candidate, is suspected to have a role in embryonic cardiac development mediating the functions of transcription factors in the developing heart." (PMID 22715383, 2012). "Indeed, loss of CDKN2A in one EHE GEMM was found to cooperate with the WWTR1::CAMTA1 fusion to enhance tumor progression." (PMID 39283723, 2024). "In addition, tumours displayed CAMTA1 positivity if they harboured a CAMTA1 fusion and TFE3 positivity in the one tumour harbouring a TFE3 fusion." (PMID 37686662, 2023). "CAMTA1 expression reduces neurosphere formation and tumor growth in nude mice." (PMID 28430789, 2017). "Recently, a study described the mechanism of action of a WWTR1(TAZ)-CAMTA1 fusion oncoprotein, and the results suggested that the WWTR1-CAMTA1 fusion might cause resistance to anoikis and the oncogenic transformation of tumor cells." (PMID 26840265, 2016).
tumor (continued). "As CAMTA1 has been reported to be a critical tumor suppressor in many cancers, and also because of its nearby genomic location to lncCAMTA1, we first evaluated whether lncCAMTA1 could regulate CAMTA1 expression in HCC cells." (PMID 27669232, 2016). "Little is known about CAMTA1; however, evidence suggests it may function as a tumour suppressor." (PMID 37296967, 2023). "The results showed that CAMTA1 could regulate tumor proliferation as an antitumor gene." (PMID 36159397, 2022). "Previous genetic studies have identified candidate neuroblastoma tumor suppressor genes, including KIF1Bb, CHD5, miR-34a, ARID1A, and CAMTA1 located at 1p36." (PMID 34885007, 2021). "At least five genes located at 1p36 (CHD5, CAMTA1, KIF1B, CASZ1, and MIR34A) were already suggested to be tumor suppressors." (PMID 34956867, 2021). "Unlike previous reports which claimed mutually exclusive occurrence of WWTR1-CAMTA1 translocation and YAP1-TFE3 gene fusion, tumor cells from the TFE3-positive EHEs showed separate signals, indicating the presence of CAMTA1 translocations." (PMID 26840265, 2016). "Tumor cells had fusiform and oval nuclei with mild atypia, and intracytoplasmic vacuoles, imparting a signet-ring like appearance, with CAMTA1-immunonegativity but WWTR1::CAMTA1 fusion." (PMID 40040722, 2025). "CAMTA1 positivity is highly specific for the diagnosis of EHE, as none of other tumor cells reacted to this antibody." (PMID 38741104, 2024). "Detection of CAMTA1-WWTR1 fusion by FISH or RT-PCR, or nuclear CAMTA1 expression at immunohistochemistry, is useful to confirm the diagnosis of HEH, as this fusion has not been identified in other human tumours." (PMID 33205035, 2021). "Moreover, by immunohistochemistry (IHC), the tumor showed diffuse reactivity for vascular markers, including ERG, CD31, CD34, and D2-40, as well as for TFE3, while being negative for MUC4, CAMTA1, smooth-muscle actin, desmin, S100 and keratins." (PMID 40879254, 2025). "All tumor types except for EHE showed limited, weak or no CAMTA1 reactivity." (PMID 27515856, 2016).